NTN1 (netrin 1)
Diseases named in the same sentence as NTN1 in open-access papers (continued):
Sharing a sentence is not in itself a finding about the gene and the disease.
glioma (11 papers, 2011 to 2024). A benign or malignant brain and spinal cord tumor that arises from glial cells (astrocytes, oligodendrocytes, ependymal cells). "We also found that up-regulation of netrin-1 was positively associated with glioma grade, malignancy, and progression in clinical glioma cases." (PMID 28710382, 2017). "Glioma tissue microarrays were stained with immunohistochemistry and the results were used to evaluate the association between netrin-1 and survival of glioma patients." (PMID 28069038, 2017). "To validate the association between netrin-1 and glioma recurrence, we assessed netrin-1 expression in paired primary and recurrent samples (n = 16) using IHC." (PMID 28710382, 2017). "In tissue microarray analysis of gliomas NTN1 was strongly linked to poor patient prognosis and especially to tumors of astrocytic origin." (PMID 28069038, 2017). "Taken together, these clinical data clearly suggested that netrin-1 may act as a diagnostic marker in glioma and play a role in the gliomas proliferation." (PMID 28710382, 2017). "Netrin-1 expression associated with poor patient prognosis in grade II-III gliomas." (PMID 28069038, 2017). "We report here that NTN1 is associated with poor patient prognosis in low grade gliomas." (PMID 28069038, 2017). "Interestingly, NTN1 positivity was associated with poor glioma-specific survival (hazard ratio [HR] = 1.73, 95% confidence interval [95% CI] = 1.11 to 2.71; p = 0.015) and with shorter recurrence-free survival time (HR = 1.62, 95% CI = 1.04 to 2.53; p < 0.001)." (PMID 28069038, 2017). "In glioma tissues, the expression of NTN1 was increased and positively correlated with tumour grade and malignancy." (PMID 38546656, 2024). "Shimizu demonstrated that an important process in the mechanism of Netrin-1–induced glioma angiogenesis and increased glioma invasiveness is cathepsin B–dependent." (PMID 37398678, 2023). "Immunohistochemical data from The Human Protein Atlas shows examples of positive Netrin-1 staining in glioma samples, with a diffuse pattern of expression." (PMID 34361013, 2021). "To assess the importance of netrin-1 in glioma tumorigenesis, we firstly measured netrin-1 expression in 16 paired fresh glioma specimens." (PMID 28710382, 2017). "The higher netrin-1 staining observed in high-grade gliomas and recurrent glioma further suggested that netrin-1 was an important factor in glioma progression." (PMID 28710382, 2017). "To determine the mechanism by which netrin-1 promoted glioma proliferation, we examined all the known netrin-1 receptors in the adult mouse brain." (PMID 28710382, 2017). "The Oncomine data supported our findings that netrin-1 expression was elevated in clinical glioma samples." (PMID 28710382, 2017). "Taken together, these results suggested that netrin-1 also regulated glioma cell proliferation and was involved in glioma tumorigenesis in vivo." (PMID 28710382, 2017). "Both Ki-67 index and elevated netrin-1 expression were found to be independent factors for distinguishing low-grade gliomas and high-grade gliomas." (PMID 28710382, 2017). "Exogenous netrin-1 enhanced glioma cell proliferation in a dose-dependent manner, and the most effective concentrations were 40–60 ng/ml for U251 cells, 20–60 ng/ml for U87MG cells, and 10–80 ng/ml for SHG44 cells." (PMID 28710382, 2017). "Because NTN1 expression correlated with nestin positivity in human glioma TMA we analyzed nestin expression in the GBM xenografts." (PMID 28069038, 2017). "We found that elevated netrin-1 expression discriminated low-grade gliomas from high-grade gliomas (AUC = 0.758, p = 0.025) and distinguished the primary gliomas from recurrent gliomas (AUC = 0.783, p = 0.006)." (PMID 28710382, 2017). "Collectively, these results showed that netrin-1 was involved in glioma cell proliferation in vitro." (PMID 28710382, 2017). "We incubated recombinant netrin-1 with the glioma cells to examine the effects of netrin-1 on cell proliferation." (PMID 28710382, 2017).
glioma (continued). "After identifying a correlation between netrin-1 and glioma malignancy, we next investigated the correlation of netrin-1 expression with several known glioma parameters." (PMID 28710382, 2017). "We found that netrin-1 was significantly increased in glioma samples and positively correlated with cell proliferation, tumor grade and malignancy." (PMID 28710382, 2017). "To further explore how netrin-1 promotes glioma progression, we examined the role of netrin-1 in three cultured human glioma cell lines, U251, U87MG and SHG44." (PMID 28710382, 2017). "Real-time PCR assay also revealed an average of 2.966-fold (n = 6, p = 0.04) increase of netrin-1 mRNA in glioma tissues." (PMID 28710382, 2017). "To address this we used immunohistochemical stainings and analyzed NTN1 expression in tissue microarrays (TMAs) consisting of 136 representative primary glioma samples." (PMID 28069038, 2017). "In the present study, we have provided direct evidence netrin-1 in glioma cells increases proliferation and regulates brain tumor growth, implying an important role of netrin-1 in gliomagenesis." (PMID 28710382, 2017). "Netrin-1 enhances c-Myc expression via NF-κB to promote glioma cell proliferation at least in part via UNC5A." (PMID 28710382, 2017). "We firstly found that netrin-1 was up-regulated in glioma tissues and positively correlated with glioma cell growth." (PMID 28710382, 2017). "Importantly, endogenous DCC has previously been demonstrated to render several glioma cell lines migratory in response to a gradient of NTN1 as a chemoattractant." (PMID 33871356, 2021). "In agreement with that, the in silico analysis shows a positive correlation between the expression of this ligand and different angiogenic-related genes such as VEGFA, ANGPT-1, and ANGPT-2, supporting a possible role for Netrin-1 in the processes of glioma vascularization." (PMID 34361013, 2021). "Taken together, these results suggested netrin-1 promotes glioma cell proliferation by activating NF-κB signaling via UNC5A, netrin-1 may be a potential therapeutic target for the treatment of glioma." (PMID 28710382, 2017). "We have demonstrated that netrin-1 was up-regulated in clinical glioma samples." (PMID 28710382, 2017). "Here, we provide evidence suggested that Netrin-1 has a critical role in glioma growth." (PMID 28710382, 2017). "Therefore, we have theorized that netrin-1 activates NF-κB via UNC5A to promote glioma cell proliferation." (PMID 28710382, 2017). "Taken together, these results describe NTN1 as a powerful regulator of glioma invasiveness." (PMID 28069038, 2017). "In our results, we found that netrin-1 induced activation of the NF-kB pathway through enhancing p65ser536 phosphorylation and mediating nuclear translocation, suggesting it is an activator of the classical NF-kB pathway in the glioma proliferation." (PMID 28710382, 2017). "Thus, taking into account the multiple roles of netrin-1 in glioma proliferation, migration and invasion, netrin-1 is going to be an innovative anticancer target for glioma treatment." (PMID 28710382, 2017). "In the present study, we showed that netrin-1 was up-regulated in glioma tissues." (PMID 28710382, 2017). "Thus in our studies we set up a linkage between the elevated netrin-1 expression and the activated NF-κB signaling pathway to promote glioma cells proliferation." (PMID 28710382, 2017). "Netrin-1 expression was substantially higher in recurrent glioma than primary glioma specimens." (PMID 28710382, 2017). "We found that UNC5A had a reasonable expression level in the tested glioma cells and glioma patients, suggesting it may mediate the cellular effects of netrin-1 in glioma." (PMID 28710382, 2017). "Furthermore, NF-κB p65ser536 phosphorylation and high c-Myc expression corresponded with elevated netrin-1 expression in grade IV clinical glioma samples." (PMID 28710382, 2017). "Elevated netrin-1 alters the glioma into more invasive phenotype." (PMID 28710382, 2017).
glioma (continued). "Netrin-1 Knockdown reduced glioma cell proliferation both in vitro and in vivo." (PMID 28710382, 2017). "To identify the molecular mechanisms by which netrin-1 promoted cell proliferation and glioma growth, we examined the expression levels of several key molecules related to cell proliferation and the cell cycle, including c-Myc, cyclin D1, p27, cyclin E and cdk2 in U251 and U87MG cells." (PMID 28710382, 2017). "Therefore, targeting Netrin-1– and cathepsin B–dependent pathways may be a new strategy for glioma therapy." (PMID 37398678, 2023). "Furthermore, our results demonstrated that up-regulation of netrin-1 was positively correlated with the cellular proliferation index Ki-67, indicating that netrin-1 may play a role in the glioma proliferation." (PMID 28710382, 2017). "However, little is known regarding how netrin-1 regulates glioma progression." (PMID 28710382, 2017). "Thus it is tempting to speculate that up-regulation of netrin-1 may enhance survival signaling through its receptors in glioma." (PMID 28710382, 2017). "However, the role of netrin-1 in glioma remains largely unknown." (PMID 28710382, 2017). "Therefore, we hypothesized that NTN1 affects the glioma stem-like cells." (PMID 28069038, 2017). "Moreover, the tumor state could be determined because it has been described that overexpression of Netrin-1 is related to type III and IV gliomas." (PMID 34361013, 2021). "Finally, it has been described that the expression of C-MYC in GBM can also be induced through the interaction of Netrin-1 and the UNC5A receptor, and that this interaction could promote the growth of gliomas through the induction of C-MYC, mediated by activation of the NF-κB pathway." (PMID 34361013, 2021).
Hyperglycemia (11 papers, 2011 to 2025). An increased concentration of glucose in the blood. "Acute renal ischemia and hyperglycemia during DKA stimulate netrin- 1 excretion by the kidney which has a vascular protective, anti-inflammatory, and antiproteinuric effect on renal tubules trying to spare the tubules." (PMID 40332546, 2025). "We found that hyperglycemia downregulates netrin-1 expression in corneal epithelium, and the subconjunctival injection of netrin-1 promotes corneal epithelial wound healing and nerve regeneration in diabetic mice." (PMID 36589805, 2022). "Our findings suggest that in hyperglycemia, netrin-1 maintains levels of p-eNOSser1177 through activation of p-ERK1/2." (PMID 29059224, 2017). "In vitro studies had shown that hyperglycemia downregulates netrin-1 expression whereas addition of high concentration of protein BSA induced netrin-1 in the same cells." (PMID 24991088, 2014). "However, hyperglycemia significantly decreases the expression of netrin-1, negatively impacting wound healing capabilities." (PMID 40723793, 2025). "Since hyperglycemia is considered a primary cause of diabetic VED, we examined levels of netrin-1 and its downstream pathway in BAECs exposed to normal glucose (NG, 5.5 mmol/L), high glucose (HG, 25 mmol/L) or mannitol (5.5 mmol/L D-Glucose + 19.5 mmol/L mannitol) media for 48 hrs." (PMID 29059224, 2017). "Decreased expression of axon guidance pathway genes, Robo1, Ntn1, Ntng1, Nrp1, and Efnb3 in NSCs exposed to hyperglycemia was suggestive that miRNAs could target and deregulate the axonal guidance pathway as predicted by the pathway analysis." (PMID 28798665, 2017). "However, whether hyperglycemia itself can induce enhanced netrin-1 production from renal tubular epithelial cells is unknown." (PMID 22046354, 2011). "Increased glucose concentration has an opposite effect on netrin-1 production, suggesting that hyperglycemia itself is not a signal for the enhanced netrin-1 production seen in vivo." (PMID 22046354, 2011).
ischemia (11 papers, 2011 to 2022). A hypoperfusion of the BLOOD through an organ or tissue caused by a PATHOLOGIC CONSTRICTION or obstruction of its BLOOD VESSELS, or an absence of BLOOD CIRCULATION. "Taken together, these studies indicate robust netrin-1 expression predominantly in renal epithelia, and suggest that mice with partial netrin-1 deficiency can be used as a model to study endogenous netrin-1 during ischemia-induced AKI." (PMID 21625583, 2011). "During ischemia–reinventing blood flow, netrin-1 enzyme is significantly down-regulated, UNC-5B mRNA expression is increased, and the DCC receptor is not changed significantly." (PMID 31663032, 2019). "We observed the empty-positive cells in the peri-ischemia region and detected the expression of Netrin-1 to ensure that AAV-NT-1 was transferred to the target area and functioned well." (PMID 29487502, 2018). "We also attempted to determine the angiogenic capacity of Ntn-1 on hindlimb ischemia in the mouse model using a laser Doppler imager." (PMID 27881869, 2016). "Other studies suggest that netrin-1 signaling via activation of the UNC5B receptor protects the kidneys from ischemia." (PMID 21625583, 2011). "We have chosen this netrin-1 dose based on previous studies testing different netrin-1 doses (0.5, 1, 5, 10 μg/mouse I.V.)showing the strongest renal protection from ischemia injury with 5 μg/mouse." (PMID 21625583, 2011). "Recent studies in the kidney showed that exogenous netrin-1 treatment in mice or renal ischemia in mice overexpressing renal netrin-1 attenuated kidney injury following ischemia." (PMID 21625583, 2011). "Consistent with current findings, a recent study indicates that PMN-dependent netrin-1 can function to provide cardioprotection during in situ ischemia and reperfusion injury by enhancing extracellular adenosine signaling events through the Adora2b adenosine receptor." (PMID 36247475, 2022). "In addition, it has been shown that the release of Netrin-1 and NO decreases with decreasing ischemia." (PMID 32455061, 2020). "Contrary to these studies, others reported that netrin-1 reduced ischemia-reperfusion injury by decreasing apoptosis in endothelial cells and that netrin-1 enhanced focal neovascularization, reduced infarct size, and improved long-term functional recovery after transient focal cerebral ischemia." (PMID 25143950, 2014). "Together, these studies indicate that ischemia-induced AKI is more severe in Ntn-1+/− mice." (PMID 21625583, 2011). "Therefore, Netrin-1 can serve as a candidate to ameliorate ischemia-induced neural damage." (PMID 29487502, 2018). "In mice, a lack of anti-inflammatory proteins, such as netrin-1, has been shown to elevate renal and systemic inflammatory markers, as well as enhancing ischemia and reperfusion kidney dysfunction; in such mice, treatment with netrin-1 has been found to restore a normal phenotype during AKI." (PMID 22235348, 2012). "Interestingly we could show a tremendous increase of netrin-1 in renal tissue and urine following ischemia in wild-type control mice compared to Ntn-1+/− mice, whereas serum concentrations were not detectable assuming that netrin-1 expression occurs mainly in renal epithelial cells." (PMID 21625583, 2011).
gastric cancer (10 papers, 2014 to 2025). A primary or metastatic malignant neoplasm involving the stomach. "In gastric cancer, Netrin-1 expression correlates with neural invasion and lymph node metastasis, and silencing Netrin-1 or its receptor neogenin significantly impairs cancer cell migration along neurites both in vitro and in vivo." (PMID 41009819, 2025). "It was also reported that NTN1 promoted gastric cancer cell proliferation via activation of FAK/ERK/MAPK." (PMID 35974411, 2022). "Increased expression levels of NTN1 in gastric cancer samples have been found in patients with stage III and IV CRC, indicating that NTN1 overexpression may promote tumour metastasis." (PMID 36831381, 2023). "Because UNC5C and DCC both serve as dependence receptors for netrin-1, we investigated whether defects in these receptors accumulate in a systematic or stochastic manner during the progression of gastric carcinoma." (PMID 26207151, 2015). "Moreover, only ablation of neogenin-1 reduced gastric cancer cell proliferation and migration, whereas ablation of netrin-1 had little effect." (PMID 24930499, 2014). "NSUN2 also increases Netrin 1(NTN1) expression and stabilizes NTN1 mRNA by enhancing m5C modification, affecting gastric cancer cell migration and NI potential." (PMID 39791162, 2025). "In gastric cancer, the PI3K-AKT pathway was shown to be induced by netrin-1 and phosphatidylethanolamine-binding protein 4 (PEBP4) both of which are proteins commonly found in many cancers." (PMID 32212786, 2020). "Our results suppose that the effect of neogenin-1 on the proliferation and migration gastric cancer cells and is independent of its ligand netrin-1." (PMID 24930499, 2014). "Neogenin-1 ligands netrin-1 and RGMa were expressed at low levels or not at all in gastric cancer cells, respectively." (PMID 24930499, 2014). "The cell migration by ablation of neogenin-1 distinctively lessened the migration of 5 of the gastric cancer cells except SNU-216, whereas the ablation of netrin-1 had no significant reduction." (PMID 24930499, 2014).